GALNT6 (polypeptide N-acetylgalactosaminyltransferase 6)
Diseases named in the same sentence as GALNT6 in open-access papers (continued):
Sharing a sentence is not in itself a finding about the gene and the disease.
colon cancer (2 papers, 2021 to 2022). "Thus, when the characteristic colon-cancer-associated expression of GALNT6 was replicated in the LS174T model, normal cell differentiation was inhibited." (PMID 33617880, 2021). "Similarly, a characteristic de novo expression of the GALNT6 isoenzyme in colon cancer was investigated by engineering GALNTs in a colon cancer cell line, and GALNT6 was selectively shown to affect differentiation and growth." (PMID 33617880, 2021). "In a cohort of 81 colon cancer specimens, patients expressing GALNT6 had a significantly increased overall survival compared with GALNT6-negative patients." (PMID 35692787, 2022). "Since KRAS and BRAF gene mutations are frequently present in colon cancers, we asked whether KRAS and BRAF mutations were more prevalent in GALNT6-negative tumors." (PMID 35692787, 2022).
ductal carcinoma in situ (2 papers, 2021). "In addition, GALNT6 has been found to be overexpressed in ductal carcinoma in situ (DCIS)." (PMID 34830771, 2021). "For example, in the development of human ductal carcinoma in situ (DCIS), the high expression of GALNT6 is closely related to the occurrence of abnormal mucin O-glycation." (PMID 35003361, 2021).
lymph node metastasis (2 papers, 2017 to 2020). "High GALNT6 expression is associated with the recurrence, lymph node metastasis, and chemoresistance of ovarian cancer." (PMID 32393740, 2020). "Here we showed that high GALNT6 expression correlates with increased recurrence, lymph node metastasis, and chemoresistance in ovarian endometrioid and clear cell carcinomas; and higher GALNT6 levels are significantly associated with poorer patient survivals." (PMID 28388560, 2017). "In this study, we found that high GALNT6 expression correlates with increased recurrence, lymph node metastasis, and chemoresistance in ovarian endometrioid and clear cell carcinomas; and higher GALNT6 level is significantly associated with poorer patient disease-free and overall survivals." (PMID 28388560, 2017). "In this subgroup, high GALNT6 expression correlated with increased recurrence, lymph node metastasis, and chemoresistance." (PMID 28388560, 2017). "The gene expression data and consecutive functional enrichment and network analysis further support the data obtained by the clinicopathological characteristics, showing that high GALNT6 expression correlates with increased recurrence, lymph node metastasis, and chemoresistance." (PMID 28388560, 2017).
prostate carcinoma (2 papers, 2019 to 2023). A carcinoma that arises from epithelial cells of the prostate gland. "Moreover, increased GALNT3 and GALNTT6 co-expression has been detected in pancreatic and prostate carcinomas, and a strong correlation between both GALNT3 and GALNT6 expression has been reported during the different stages of endometriosis." (PMID 31071912, 2019).
serous carcinoma (2 papers, 2017 to 2019). "In our study, GALNT6 associated with malignant characteristics is noted in the endometrioid and clear cell subtypes but not in the serous carcinoma." (PMID 28388560, 2017). "GALNT6 was also shown to be overexpressed in different EOC histotypes, as it was suggested that in low-grade serous carcinoma, GalNAc-T6 expression may contribute to improved long-term survival." (PMID 31071912, 2019).
clear cell carcinoma (1 paper, 2017). "In the present study, we first reported that higher GALNT6 level is associated with poorer prognosis in patients with ovarian endometrioid or clear cell carcinoma." (PMID 28388560, 2017). "In conclusion, high GALNT6 expression is associated with poor prognosis in ovarian endometrioid and clear cell carcinomas." (PMID 28388560, 2017). "However, when we examined a group of patients with ovarian endometrioid and clear cell carcinomas, the high expression of GALNT6 significantly associated with poor outcome." (PMID 28388560, 2017). "Collectively, these results confirm that GALNT6 promotes the aggressive behavior of ovarian endometrioid and clear cell carcinoma cells by regulating EGFR glycosylation and activity." (PMID 28388560, 2017).
clear cell ovarian carcinomas (1 paper, 2017). "However, further studies are still needed to verify the role of GALNT6 in the chemoresistance of endometrioid and clear cell ovarian carcinomas." (PMID 28388560, 2017). "Thus, it is tempting to speculate that GALNT6 confers a more aggressive phenotype to endometrioid and clear cell ovarian cancer cells." (PMID 28388560, 2017).
colorectal adenocarcinoma (1 paper, 2022). The most common type of colorectal carcinoma. "We used the TCGA cohort to assess the relative abundance differences of GALNT6 mRNA between colorectal adenocarcinomas and matched normal mucosa." (PMID 35692787, 2022).
colorectal tumors (1 paper, 2022). "This study examined GALNT6 protein expression in 679 colorectal tumors, including 574 early-stage and 105 late-stage cancers." (PMID 35692787, 2022).
exfoliation syndrome (1 paper, 2021). An autosomal dominant disorder caused by mutations in the LOXL1 gene, encoding lysyl oxidase homolog 1. "Linkage disequilibrium and epistasis analysis for this variant identified the genes LHFPL3, GALNT6, PIH1D1, ANKS1B, and METRNL as potentially involved in the etiopathogenesis of exfoliation syndrome and glaucoma, which were not previously associated with the disease." (PMID 34440405, 2021).
glaucoma (1 paper, 2021). Increased pressure in the eyeball due to obstruction of the outflow of aqueous humor. "In our study, the newly identified linked genes LHFPL3, GALNT6, PIH1D1, ANKS1B, and METRNL may be involved in the etiopathogenesis of XFS and glaucoma." (PMID 34440405, 2021).
myopia (1 paper, 2026). "Our meta-analysis identified seven novel suggestive loci associated with myopia progression, including FSTL5 on 4q32.2, SMARCA2 on 9p24.3, CCDC3 on 10p13, GALNT6/ACVR1B on 12q13.13, CRY1 on 12q23.3, ULK2 on 17p11.2, and MYL4/EFCAB13-DT on 17q21.32." (PMID 42094695, 2026).
oral squamous cell carcinoma (1 paper, 2022). "Interestingly, an association between Galnt6 and piRNAs has been identified in an oral squamous cell carcinoma mouse model." (PMID 35721752, 2022).
ovarian serous carcinoma (1 paper, 2017). "Due to the most common histology of EOC is serous, we first examined the GALNT6 expression in 39 patients with ovarian serous carcinoma." (PMID 28388560, 2017).
pancreatic ductal adenocarcinoma (1 paper, 2023). An infiltrating adenocarcinoma that arises from the epithelial cells of the pancreas. "In the present study, the role of GALNT6 in pancreatic ductal adenocarcinoma cells was investigated." (PMID 36925932, 2023). "However, GALNT6 wasn’t overexpression in all PDAC cell lines, which may be linked to different types of pancreatic ductal adenocarcinoma." (PMID 36925932, 2023).
tumor (18 papers, 2014 to 2025). "Meanwhile, hypomethylation of several oncogenes such as NRG1, ITGB4 and GALNT6 associated with tumor-enriched bacteria suggests the potential of microbiota to promote host gene expression through epigenetic activation." (PMID 38589501, 2024). "Based on immunohistochemical staining distribution, we defined GALNT6 positivity as ≥10% of tumor cells showing GALNT6 expression and, conversely, loss of GALNT6 expression as cases with <10% of tumor cells staining." (PMID 35692787, 2022). "Moreover, another study outlined deficient mismatch repair (dMMR) CRC molecular subtype tumours displayed significantly downregulated expression of GALNT6, a prominent glycosyltransferase in glycan synthesis." (PMID 39348343, 2024). "Importantly, it is also O-glycosylated by a polypeptide GalNAc-transferases (GALNT2 and GALNT6) that add the first GalNAc to serine or threonine amino acids giving rise to tumor-associated Tn-antigen." (PMID 35028012, 2022). "However, loss of GALNT6 expression was significantly correlated with high tumor grade." (PMID 35692787, 2022). "The results of this study provide new insight into the roles of GALNT6 in tumor development and a potential treatment for PDAC." (PMID 36925932, 2023). "The volume and weight of the tumors formed in mice were assessed, and the results showed that both tumor size and volume were significantly decreased in tumors formed of the GALNT6 knockdown cells." (PMID 35003361, 2021). "By day 60 post inoculation, while all of the PC9-shNC tumor-bearing mice died, 50% of the mice bearing PC9-shG6-1 tumors survived indicating that GALNT6 silencing prolonged the survival of tumor-bearing mice (P < 0.01)." (PMID 32393740, 2020). "Accordingly, GALNT3/T6 KO-derived tumor tissues showed reduced staining intensity for all of GALNT6, FN1, and MUC1 when compared with the Ctrl and GALNT3 KO tissues." (PMID 31071912, 2019). "GALNT6 was significantly up-regulated in tumor tissues in all stages, but the trend of up-regulation showed a decline from stage III to stage IV LUAD patients." (PMID 31296175, 2019). "Of the three investigated glycosyltransferases, GALNT6 seems to offer the best correlations with regard to tumour size and grading." (PMID 26161413, 2015). "Mutations in gene Ccdc93 are associated with several cancers in humans, with similar observations are for Galnt6, which is probably involved in breast cancerogenesis through O-glycan processing (GO:0016266)." (PMID 25079915, 2014). "Similarly, a positive correlation was found between P. stomatis abundance and GALNT6 expression (involved in tumor progression and metastasis) (rho = 0.511, p = 0.001)." (PMID 38589501, 2024). "Similarly, it is commonly recognized that GALNT6, another GalNAc-T family member, impedes tumor growth and progression when losing expression." (PMID 38022687, 2023). "Since the number of GALNT6-expressing tumor cells varied widely between different patients’ cancers (and much more than staining intensity/abundance per cell), we took a semi-quantitative approach and determined the fraction of GALNT6-positive tumor cells for all cases in our cohort." (PMID 35692787, 2022). "Furthermore, GALNT6 knockdown suppressed tumor growth in vivo." (PMID 35003361, 2021). "In ER− patients, the result from the PPI networks of the tumours with the high expression of cytoplasmic CAIX demonstrated that two proteins, namely, GALNT6 and MUCL1, had significant interactions with each other." (PMID 39660488, 2024). "GALNT6 can promote EMT25,26, but how it affects tumor invasion and metastasis is not completely known." (PMID 32393740, 2020). "GALNT6 expression intensity varies greatly between these specimens, ranging from no cells to virtually all tumor cells expressing the enzyme." (PMID 35692787, 2022).
cancer (16 papers, 2014 to 2025). A tumor composed of atypical neoplastic, often pleomorphic cells that invade other tissues. "Loss of GALNT6 occurred in 9.9% of early-stage and 15.2% of late-stage cancers and was more prevalent in grade 3 or MSI subtype tumors." (PMID 35692787, 2022). "It was previously reported that GALNT6 is implicated in the EMT process which is crucial for cancer metastasis and poor prognosis." (PMID 32393740, 2020). "Because loss of protein expression of GALNT6 is prognostic in early-stage cancer patients, we asked whether a similar trend would be observed at the level of GALNT6 mRNA expression." (PMID 35692787, 2022). "In addition, GALNT6 is implicated in the epithelial–mesenchymal transition (EMT) process which is crucial for cancer metastasis." (PMID 32393740, 2020). "When cancer cells retain secretory polarity, GALNT6 is expressed on the luminal/apical side, similar to expression observed in benign enterocytes." (PMID 35692787, 2022). "When expressed by cancer cells, GALNT6 expression is mostly cytoplasmic in a granular pattern near the nucleus." (PMID 35692787, 2022). "GALNT6 expression in cancer tissue varied widely between patients ranging from high levels to complete loss." (PMID 35692787, 2022). "KRAS wild-type cancers had lower GALNT6 mRNA expression levels than KRAS mutated cancers, whereas BRAF mutated tumors had lower GALNT6 mRNA expression levels than BRAF wild-type tumors." (PMID 35692787, 2022). "GALNT6 mRNA is increased in a majority of carcinomas (median z-score, +2.922; 25th/75th percentile z-scores, +2.182/+3.684)." (PMID 35692787, 2022). "The extent to which GALNT6 upregulation exerts any effect appears to be dependent on the type of cancer in question." (PMID 35003361, 2021). "The protein expression levels of GALNT6 in 10 CRC clinical samples were assessed, and the results demonstrated that GALNT6 was also highly expressed in these cancer tissues." (PMID 35003361, 2021). "Secondly, we tested the effect of altered GALNT6 expression on EMT in cell lines to assess the ability of cancer cells to metastasize." (PMID 32393740, 2020). "PI3K/Akt and MAPK/ERK signaling pathways were involved in GALNT6 or other GALNTs-induced cancer metastasis." (PMID 32559179, 2020). "Polypeptide N-acetylgalactosaminyltransferase 6 (GALNT6) is an enzyme for O-glycosylation and its expression is increased in some human cancers, including lung adenocarcinoma." (PMID 32393740, 2020). "Our previously published data were also indicative of a possible functional overlap of the GALNT3 and GALNT6 enzymes in cancer." (PMID 31071912, 2019). "Aberrantly expressed O-glycans have been reported in many cancers; however, the roles of GALNT6 in cancers remain largely unclear." (PMID 28388560, 2017). "Although Phactr1 and Galnt6 have not been directly implicated in trophoblast cell biology, they have been shown to regulate migration and invasion of cancer cells." (PMID 37417811, 2023). "Because better risk stratification is particularly crucial for treatment decisions in early-stage cancer, we examined whether GALNT6 protein expression is potentially prognostic." (PMID 35692787, 2022). "The expression of GALNT6 in 20 types of cancers was evaluated using the Oncomine database." (PMID 32559179, 2020). "Previous studies suggest that GALNT6 may be important for cancer formation, progression, metastasis, and prognosis." (PMID 32393740, 2020). "Numerous studies indicate that abnormal expression of GALNT6 may be important for cancer formation, progression, metastasis and prognosis." (PMID 32393740, 2020). "Although α2M was reported to be able to play an oncogenic role in cancers, it remained unclear whether α2M was involved in GALNT6 promoting metastasis, or whether GALNT6 could mediate mucin-type O-glycosylation of α2M." (PMID 32559179, 2020). "Regarding initiation of GalNAc-type O-glycosylation, GALNT2, GALNT3, GALNT6, GALNT7, and GALNT14 were highly expressed in both cancer types, LUAD and LUSC." (PMID 40718829, 2025).
cancer (continued). "Since mucins are abundant in the lower intestinal tract and constitute major substrates of GALNT enzymes, we studied correlations between GALNT6 and mucins (MUC) genes using the 508-case TCGA cancer dataset." (PMID 35692787, 2022). "Among these cancer cell lines, ES-2 and OVTW59 cells expressed higher levels of GALNT6, whereas SKOV3 and A2780 cells expressed lower levels of GALNT6." (PMID 28388560, 2017). "Judging by the expression distributions, GALNT6 expression appears to decrease as the cancers advance, and cases of late-stage cancer are more likely to show negative or reduced GALNT6 expression." (PMID 35692787, 2022). "GALNT6 protein expression was further assessed using UALCAN, which showed GALNT6 protein expression was significantly upregulated regardless of cancer stage." (PMID 35003361, 2021). "All these genes (AP2M1, FKBP11, GALNT6, BDNF, COL9A3 and NR4A1) favor relevant features of cancer progression, indicating that their epigenetic activation in CTCs of CRC patients under treatment could be a key event for the development of therapy resistance and cancer progression." (PMID 38188020, 2023). "Among late-stage cancer cases, 46.2% (6/13) of MSI tumors and 10.9% (10/92) MSS tumors were GALNT6-negative." (PMID 35692787, 2022). "Among early-stage cancer cases, 26.3% (35/133) of MSI tumors were GALNT6-negative but only 5.0% (22/441) of MSS tumors were GLANT6-negative." (PMID 35692787, 2022).
GALNT6 also shares sentences with these, for which no sentence is quoted: renal cell carcinoma (2 papers); breast (1); cervical cancer (1); endometriosis (1); hepatocellular carcinoma (1); invasive breast carcinoma (1); liver cancer (1); neuroblastoma (1); non-small cell lung carcinoma (1); serous ovarian cancer (1); uveal melanoma (1).